RNU7-106P (RNA, U7 small nuclear 106 pseudogene)
Gene: Small nuclear RNA gene on chromosome 12 (80,068,691 to 80,068,757, reverse strand). Ensembl gene ENSG00000238842.
Homologues: Orthologues: macaque U7 (96% identical). Paralogues in human: RNU7-25P (79% identical), RNU7-7P (79% identical), RNU7-11P (78% identical), RNU7-22P (76% identical), RNU7-40P (76% identical), RNU7-46P (76% identical), RNU7-47P (76% identical), RNU7-14P (75% identical), RNU7-186P (75% identical), RNU7-18P (75% identical), RNU7-19P (75% identical), RNU7-21P (75% identical), and 143 more.